TIGAR (TP53 induced glycolysis regulatory phosphatase)
Diseases named in the same sentence as TIGAR in open-access papers (continued):
Sharing a sentence is not in itself a finding about the gene and the disease.
cancer (continued). "Another major function of TIGAR in cancer metabolism is to increase the level of NADPH and lower the intracellular level of ROS." (PMID 26934324, 2016). "High TIGAR expression correlated with the increased tumor survival/burden, while TIGAR depletion promoted the apoptosis rate of cancer cells." (PMID 27884166, 2016). "In short, TIGAR is essential in cancer glucose metabolism, and has the potential to be a novel therapeutic target for cancer therapy." (PMID 26934324, 2016). "In summary, our data indicate that TIGAR reduces anti-cancer drug- andhypoxia-induced DNA damage and enhances DNA repair through increasing generation ofNADPH and ribose." (PMID 25928429, 2015). "Overall, TIGAR was overexpressed in 27/36 (75%) of the NPC tissues compared with the adjacent non-cancer epithelial cells." (PMID 25621025, 2015). "This evidence suggested that TIGAR confers a protective function to cancer cells within multiple tissue types." (PMID 25621025, 2015). "The situation seems somewhat clearer in cancer development, where overexpression of TIGAR is found in several tumor types and the deletion of TIGAR corresponds to a delay in cancer development." (PMID 24383451, 2014). "It is clear that PFK-2/FBPase-2 enzymes and TIGAR are important players in the control of cancer cell metabolism." (PMID 24280138, 2013). "TIGAR expression deregulation was shown to be relevant in oncogenesis and cancer progression." (PMID 40277923, 2025). "In 2015, TIGAR expression and its correlation with the various cancer stages were investigated." (PMID 40277923, 2025). "Its tumor-suppressive function may stem from this metabolic shift; by restricting glycolytic energy production, TIGAR can inhibit cancer cell proliferation." (PMID 41345520, 2025). "Highlighting the significance of TIGAR in the field of cancer research and treatment due to its role in metabolic reprogramming, oxidative stress regulation, tumor progression, and its dual function in both promoting and inhibiting cancer makes it a complex but promising therapeutic target." (PMID 40277923, 2025). "TIGAR overexpression has been associated with different human cancer types, and TIGAR relevance was never assessed in ESCC." (PMID 40277923, 2025). "However, in both mouse and human cancers, progression to invasive primary tumors was accompanied by a clear decrease in TIGAR expression." (PMID 40277923, 2025). "Furthermore, we will explore the potential role of TIGAR as a biomarker for cancer diagnosis and its possible applications as a therapeutic agent." (PMID 40277923, 2025). "TIGAR protects cancer cells from programmed cell death, supporting their progression and growth through inhibiting glycolysis; therefore, shifting metabolism to the pentose phosphate pathway and producing NADPH and glutathione as antioxidants and ribose-5-phosphate for nucleotide synthesis." (PMID 40277923, 2025). "Additionally, TIGAR supports cancer cell survival by activating DNA repair through PPP in a CDK5-ATM-dependent signaling pathway, in response to hypoxia or DNA damage." (PMID 40076651, 2025).
cancer (continued). "Taken together, these results suggested that modulation of TIGAR expression in the cancer cells (resulting in increased or decreased ROS) could control the accumulation of tumor-promoting fibroblasts." (PMID 39636862, 2024). "Therefore, autophagic CAFs prevent cancer cell death by providing substrates for metabolic activity of cancer cells and upregulating TIGAR which confers resistance to tamoxifen-induced apoptosis and autophagy." (PMID 37065872, 2023). "In addition, overexpression of TIGAR in cancer cells induces a glycolytic phenotype in CAFs and promotes the expression of HIF-1 α, PFKFB3 (6-phosphofructo-2-kinase/fructose-2,6-biphosphatase 3) and lactate dehydrogenase-A along with increasing glucose uptake." (PMID 37065872, 2023). "Further, TIGAR can be a possible target protein for the therapeutic intervention of cancer cells." (PMID 36518138, 2022). "Therefore, understanding the mechanisms that drive TIGAR overexpression in cancer cells is crucial to unveil how the antioxidant potential of this enzyme can be blocked." (PMID 35163828, 2022). "Therefore, researchers are more interested in the role of TIGAR in cancer due to its function in glycolysis and redox balance." (PMID 35574353, 2022). "TIGAR is highly expressed in many cancer cells to promote cell survival." (PMID 36437984, 2022). "The main aim of the present study was to determine whether NRF2 can transcriptionally regulate the expression of TIGAR in human carcinoma cells." (PMID 35163828, 2022). "Notably, PPP remains active via upregulation of TIGAR in the FBP1-loss basal-like subset, indicating the importance of PPP in catabolic cancer metabolism." (PMID 32927665, 2020). "However, in both mouse and human cancers, progression to invasive primary tumors was accompanied by a clear decrease in TIGAR expression, consistent with the selection for cells with higher ROS and higher invasive capacity during these stages of tumorigenesis." (PMID 31983610, 2020). "Since TIGAR amplification and overexpression have been found in many types of human primary cancer based on our analysis on TCGA data, our results in the current study may extend to other cancer types where TIGAR is overexpressed." (PMID 32206103, 2020). "However, elevated expression of TIGAR has also been detected in many cancer types, consistent with a role for antioxidants in tumor progression." (PMID 31983610, 2020).
cancer (continued). "TIGAR is amplified in different cancer types and its down-regulation sensitizes cancer cells to PARP inhibitors through inhibition of the pentose phosphate pathway, increase in ROS and DNA damage, down-regulation of BRCA1/2 and RAD51, and induction of cellular senescence." (PMID 32029455, 2020). "Finally, targeting TIGAR in cancer presents a potential strategy to overcome PARP inhibitor resistance and to prevent tumor progression." (PMID 31508509, 2019). "It was reported that TIGAR protects cancer cells against ROS-induced cell apoptosis." (PMID 31799200, 2019). "The down-regulation of TIGAR has been correlated with cancer growth inhibition." (PMID 31799200, 2019). "Interestingly, we observed that TIGAR KD by itself significantly (**p < 0.01) decreased colony formation, and similar results were observed in another cancer cells OVCA420*, suggesting that TIGAR depletion attenuates the growth of cancer cells." (PMID 31508509, 2019). "One potentially promising aspect of targeting TIGAR in cancer is that it regulates Warburg effect." (PMID 31508509, 2019). "Targeting TIGAR may induce “BRCAness” in cancer cells and serve as a combination strategy to overcome PARP inhibitor resistance or to enhance PARP inhibitor therapeutic effects." (PMID 31508509, 2019). "The increased DNA damage and sensitivity to olaparib following TIGAR KD may also affect NAD+ biosynthesis because TIGAR KD decreases NAD+ precursor nicotinic acid in two cancer cell lines." (PMID 31508509, 2019). "Collectively, these results highlight TIGAR as a potential therapeutic target in cancers." (PMID 31508509, 2019). "The relationship between TIGAR and the NF-κB pathway may depend on the extracellular context and the type of cancer." (PMID 29753331, 2018). "TIGAR is involved in various biological processes of cancer cells." (PMID 29753331, 2018). "The link between TIGAR and invasion of cancer cells has been established by several studies." (PMID 29753331, 2018). "TIGAR activity could limit glycolysis and produce antioxidant molecules and precursors for nucleotide synthesis, thereby limiting cancer development." (PMID 30234009, 2018). "Consequently, autophagic CAFs supply recycled substrates for the cancer cell metabolism and, also, avoid cancer cell death by overexpressing TIGAR, thereby conferring resistance to apoptosis and autophagy." (PMID 30234009, 2018). "Like the PFKFB isoenzymes, TIGAR can also play a role in cancer." (PMID 30234009, 2018). "Moreover, when carcinoma cells overexpress TIGAR in co-cultures with fibroblasts, a glycolytic phenotype is induced in the fibroblasts, inducing HIF-1α expression as well as increasing glucose uptake and the expression of PFKFB3 and lactate dehydrogenase-A." (PMID 30234009, 2018). "TIGAR overexpression in carcinoma cells increases tumor growth and proliferation rates in vivo." (PMID 30234009, 2018). "These theoretical findings are supported by the fact that cancer cells express a specific phosphatase (TIGAR) that catalyzes the degradation of the glycolytic activator Fru26P2 in order to suppress glycolysis and to redirect the glucose flux through the oxidative pentose phosphate pathway." (PMID 26935066, 2016). "The functions of TIGAR were potentially relevant to cancer initiation and progression." (PMID 27884166, 2016). "This evidence suggests that TIGAR is a potential oncogene involved in various cancers." (PMID 25621025, 2015).
cancer (continued). "However, recent studies have revealed that deregulated TIGAR expression enhances the development of cancer by promoting the survival of cancer cells." (PMID 25621025, 2015). "Results showed that TIGAR was increasedand relocated to the nucleus after epirubicin or hypoxia treatment in cancer cells.Knockdown of TIGAR exacerbated DNA damage and the effects were partly reversed bythe supplementation of PPP products NADPH, ribose, or the ROS scavenger NAC." (PMID 25928429, 2015). "However, these mice have revealed a role for TIGAR in the response to various forms of stress, such as cancer and heart failure." (PMID 24383451, 2014). "Interestingly, during cancer progression, dynamic changes in TIGAR expression are observed." (PMID 40277923, 2025). "Therefore, TIGAR-mediated changes in ROS might be a vital mechanism for regulating the occurrence and progression of many cancers." (PMID 40277923, 2025). "Consequently, TIGAR might boost cancer cell survival in response to chemotherapy by blocking both apoptosis and autophagy." (PMID 40277923, 2025). "However, elevated expression of TIGAR has been detected in numerous types of cancers, which may be contributed to its function of promoting cell survival." (PMID 36943624, 2023). "TIGAR protein is abundant in brain, heart, kidney, skeletal muscle and a variety of cancer cells." (PMID 36437984, 2022). "Since glycolysis is the major energy source for cancer cells, one would expect that inhibition of glycolysis may bring down the ATP levels in TIGAR-overexpressing ESCC cells; however, we observed a significantly elevated rather than decreased ATP level in these cells." (PMID 32206103, 2020). "Therefore, targeting TIGAR may not only deplete the cancer cells with critical substrates required for proliferation, but also deprive them with substrates required for regeneration of antioxidant." (PMID 31508509, 2019). "Hence, the MUC1‐C and TIGAR may become potential targets for the treatment of ESCC cancer, and the combination therapy of the two genes may be more effective for ESCC patients." (PMID 30523643, 2019).
cancer (continued). "Therefore, TIGAR nuclear translocation may represent an adaptation of metastatic cancer cells to environmental changes." (PMID 29753331, 2018). "Therefore, TIGAR and Met are closely related and mutually regulated in cancer." (PMID 29753331, 2018). "Furthermore, TIGAR downregulation inhibits growth in several cancer cell lines." (PMID 30234009, 2018). "In addition, TIGAR knockdown enhanced the radiosensitivity of cancer cells, suggesting that correlation of TIGAR expression and outcome of patients with CN-AML may also depend on the response of AML cells to chemotherapy." (PMID 27884166, 2016). "On the one hand, high expression of TIGAR in human cancer may protect cancer cells from cell death." (PMID 27884166, 2016). "More recent studies have suggested that TIGAR expression increases NADPH levels through activation of the pentose phosphate pathway (PPP), thereby promoting antioxidant function which reduces reactive oxygen species (ROS)-associated apoptosis and enhances cancer cell survival." (PMID 24363807, 2013). "Previous studies have shown that lactate uptake and mitochondrial metabolism are upregulated by c‐MYC, MCT1, and TIGAR, and lactate export is mediated by MCT4 and is highly expressed in glycolytic cancer cells." (PMID 39996379, 2025). "While TIGAR’s role in modulating glycolysis and maintaining redox balance is established, its specific impact on the expression of PGC-1α and NRF1 in cancer cells requires further investigation." (PMID 40277923, 2025). "TIGAR knockdown resulted in a reduced expression of both metalloproteinases MMP2 and MMP9, known for their role in tumor microenvironment formation and cancer progression and metastasis." (PMID 40277923, 2025). "A metabolic switch, known as Warburg effect, enables cancer cells to utilize higher amount of glucose by shunting glucose-6-phosphate to PPP and this PPP shunt is in part mediated by TIGAR." (PMID 31508509, 2019). "In another study, glutamine was described to increase TIGAR and be needed for CAV1 downregulation in CAFs, decreasing mediators and markers of autophagy in cancer cells." (PMID 30234009, 2018). "Indeed, it remains elusive whether TIGAR can promote cancer metastasis in vivo." (PMID 29753331, 2018). "Some recent evidences suggest that DNA damage induced by adriamycin enhances the TIGAR and TKTL1 expression and knocking down the TKTL1 or WRN complex both leads to reduced glycolytic metabolism and accumulation of DNA damage in cancer cells." (PMID 25925410, 2015). "PFKFB4 shows predominantly bisphosphatase activity, leading to the suggestion that these cancer cells rely on PFKFB4 to dampen glycolytic flux, promote the PPP and manage ROS accumulation - very similar to the proposed action of TIGAR." (PMID 24383451, 2014). "The ability of conditioned medium from the PDAC cells to influence fibroblasts suggested that the cancer cells were secreting a factor that was modulated by the presence or absence of TIGAR." (PMID 39636862, 2024).